HMGCS1 (3-hydroxy-3-methylglutaryl-CoA synthase 1)
Diseases named in the same sentence as HMGCS1 in open-access papers (continued):
Sharing a sentence is not in itself a finding about the gene and the disease.
cervical cancer (6 papers, 2020 to 2026). A primary or metastatic malignant neoplasm involving the cervix. "HMGCS1 preferentially accumulates in the mitochondria of cisplatin-resistant cervical cancer cells, and targeted expression of HMGCS1 to mitochondria, but not to the nucleus or cytosol, is sufficient to confer cisplatin resistance." (PMID 41545954, 2026). "Our findings reveal an unexpected role for HMGCS1 as a non-canonical regulator of mitochondrial transcription and establish the HMGCS1-mitochondrial transcription axis as a promising therapeutic target to overcome cisplatin resistance in cervical cancer." (PMID 41545954, 2026). "Taken together, these results suggest that TGFBR3 and HMGCS1 are negative regulators of cervical cancer development." (PMID 32491253, 2020). "In light of these current studies, we proposed that TGFBR3 or HMGCS1 suppressed cervical cancer progression through negatively regulating the Wnt/β‐catenin pathway or positively promoting phosphorylation of p27 and CHK2, at least partially." (PMID 32491253, 2020). "TGFBR3 and HMGCS1 acted as repressors of cervical cancer development, attenuating the activity of colony formation in vitro." (PMID 32491253, 2020). "Taken together, our finding provides the new STAT3‐miR‐223‐TGFBR3/HMGCS1 axis in cervical cancer development." (PMID 32491253, 2020). "Moreover, combined treatment with cisplatin and inhibitors targeting either HMGCS1 or mitochondrial transcription exhibits synergistic effects against cisplatin-resistant cervical cancer cells." (PMID 41545954, 2026). "HMGCS1 is expressed at a low level in cervical cancer based on analysis of five independent transcriptomic Gene Expression Omnibus (GEO) datasets suggesting that HMGCS1 may play another role in cancer progression." (PMID 32491253, 2020). "As the downstream targets of miR‐223, we hypothesized that TGFBR3 and HMGCS1 might function as repressors in cervical cancer development." (PMID 32491253, 2020). "However, more in‐depth investigations of the role of TGFBR3 or HMGCS1 in cervical cancer progression are required in future." (PMID 32491253, 2020). "Furthermore, stimulated Hmgcs1 exerts a radioprotective effect on cervical cancer cells." (PMID 38561516, 2024). "3-Hydroxy-3-methylglutaryl-CoA synthase 1 (HMGCS1), a metabolic enzyme that participated in terpenoid backbone biosynthesis, was demonstrated to involve in the progression of cervical cancer." (PMID 36816023, 2023). "Similarly, in cervical cancer, STAT3-miR-223 regulates HMGCS1 expression, influencing disease progression." (PMID 40642530, 2025).
colorectal cancer (6 papers, 2020 to 2025). A primary or metastatic malignant neoplasm that affects the colon or rectum. "For example, KLF13 suppressed colorectal cancer development via repressing HMGCS1 transcription." (PMID 41410190, 2025). "Unexpectedly, the expression of GPX4 and HMGCS1 in colorectal cancer was upregulated." (PMID 36552870, 2022). "Except for GPX4 and HMGCS1, the results were consistent with the expression levels in cancer tissues and normal colorectal tissues, as the expression levels decreased with the deterioration of clinicopathological conditions in patients with colorectal cancer." (PMID 36552870, 2022). "We analyzed the correlation between stemness markers and cholesterol biosynthesis genes in TCGA colorectal cancer (COADREAD) cohort and revealed positive correlations between CSC markers (EphB2 and CD44) and cholesterol biosynthesis genes (HMGCR, HMGCS1, FDPS, and FDFT1)." (PMID 34621019, 2021). "Therefore, we used the correlation of the expression level of genes with the prognosis of colorectal cancer patients as an evaluation index, and finally identified eight critical enzymes of amino acid metabolism in colon TAMs, namely, ACADM, ACADS, GPX4, GSR, HADH, HMGCL, HMGCS1 and IDH1." (PMID 36552870, 2022).
dyslipidemia (6 papers, 2005 to 2025). "Recent studies have shown that dyslipidemia can be treated by either reducing the expression of Hmgcs1 or directly inhibiting its activity." (PMID 40565139, 2025). "Ligustilide forms an irreversible bond with the Cys129 site of HMGCS1 through its metabolic intermediate, leading to a significant reduction in HMGCS1 enzyme activity and thus effectively ameliorating dyslipidemia induced by a high-fat diet in mice." (PMID 39359475, 2024). "They found that Z-LIG metabolized to EM-Lig could reduce HMGCS1 enzyme activity by attacking Cys129 of HMGCS1 to block its acetylation, thereby reducing cholesterol biosynthesis and ameliorating dyslipidemia." (PMID 39766330, 2024).
gastric cancer (5 papers, 2020 to 2024). A primary or metastatic malignant neoplasm involving the stomach. "It has been reported that HMGCS1 is positively associated with the proliferation, migration, and invasion of gastric cancer cells." (PMID 36835419, 2023). "The increase in nuclear HMGCS1 in gastric cancer cells caused by serum deprivation prompted us to investigate whether HMGCS1 is involved in modulating the ISR pathway." (PMID 32349352, 2020). "Therefore, we investigated the biological functions of HMGCS1 in controlling tumor development and the progression of gastric cancer cells and delineated the underlying mechanisms of HMGCS1-mediated gastric cancer progression." (PMID 32349352, 2020). "This study found that HMGCS1 expression is upregulated in stomach adenocarcinoma samples of patients and tumorspheres of gastric cancer cells." (PMID 32349352, 2020). "Herein, we also showed for the first time that the nuclear translocation of HMGCS1 in gastric cancer cells was induced after serum deprivation." (PMID 32349352, 2020). "Mouse models were employed to further evaluate the effect of HMGCS1 on tumor growth and the metastatic colonization of gastric cancer cells." (PMID 32349352, 2020). "HMGCS1 also promotes in vitro cell growth and progression and the in vivo tumor growth and lung metastasis of gastric cancer cells." (PMID 32349352, 2020). "HMGCS1 expression in tumors and adjacent normal tissues from gastric cancer patients was examined using immunohistochemical analysis." (PMID 32349352, 2020). "This study also demonstrated that the slight enhancement of the growth and progression of gastric cancer cells after tunicamycin-induced mild ER stress was HMGCS1-dependent." (PMID 32349352, 2020). "The results of the Kaplan‒Meier survival plot showed that gastric cancer patients with higher levels of HMGCS1 mRNA had a poorer overall survival rate." (PMID 32349352, 2020). "HMGCS1 translocates into the nuclei of gastric cancer cells under stress conditions and binds to and activates Oct4 and SOX-2 promoters." (PMID 32349352, 2020). "The results of Western blot analysis showed that HMGCS1 protein was differentially expressed in gastric cancer cells, including AGS, NUGC-3, KATO III, SNU-16, and NCI-N87 cells." (PMID 32349352, 2020). "HMGCS1 contributes to gastric cancer progression through activating Oct4 and SOX2 promoters." (PMID 36564758, 2022). "Next, the effect of HMGCS1 on the growth and progression of gastric cancer cells was analyzed." (PMID 32349352, 2020). "Furthermore, the level and nuclear translocation of HMGCS1 in gastric cancer cells are induced by serum deprivation." (PMID 32349352, 2020). "Since the HMGCS1 gene is amplified in stomach cancer, we investigated whether HMGCS1 affects gastric cancer progression." (PMID 32349352, 2020). "To assess this possibility, we first checked for HMGCS1 in the nuclei of gastric cancer cells." (PMID 32349352, 2020). "Furthermore, ER stress inducer tunicamycin augmented HMGCS1 expression in gastric cancer cells, and HMGCS1 overexpression raised levels of p-eIF2α, p-PERK, ATF4, and ER stress markers." (PMID 32349352, 2020). "Notably, HMGCS1 mRNA expression was dramatically upregulated in lymph node tumor samples from 26 gastric cancer patients with lymph node metastasis." (PMID 32349352, 2020). "Furthermore, levels of HMGCS1 in gastric cancer cells could be induced by serum deprivation, and the increase in HMGCS1 expression induced the ISR pathway." (PMID 32349352, 2020). "Therefore, HMGCS1 can activate the ISR pathway in gastric cancer cells." (PMID 32349352, 2020). "Therefore, targeting components of the ISR pathway in combination with statin and dipyridamole treatment may be a novel therapeutic strategy for the treatment of gastric cancer patients with higher levels of HMGCS1 and these components in the future." (PMID 32349352, 2020).
gastric cancer (continued). "Thus, we believe nuclear HMGCS1 could promote gastric cancer progression by directly or indirectly binding to pluripotency genes and inducing their expression." (PMID 32349352, 2020). "Additionally, HMGCS1 was detected in both the nuclei and cytoplasm of gastric cancer tissues." (PMID 32349352, 2020). "HMGCS1 elevates the expression levels of the pluripotency genes Oct4 and SOX-2 and contributes to tumorsphere formation ability in gastric cancer cells." (PMID 32349352, 2020). "Levels of mRNA and protein of HMGCS1 were enhanced in tumorspheres of KATO III and NCI-N87 gastric cancer cells compared with those in their parental cells according to quantitative real-time PCR and Western blot analysis, respectively." (PMID 32349352, 2020). "Our data also proved that HMGCS1 interacted with PERK and induced phosphorylation of PERK in gastric cancer cells." (PMID 32349352, 2020). "In summary, our results reveal that HMGCS1 exerts both metabolic and nonmetabolic functions in gastric cancer progression." (PMID 32349352, 2020). "HMGCS1 also interacts with PERK and induces the ISR pathway, suggesting that HMGCS1 and the ISR pathway may be promising targets for therapy in gastric cancer." (PMID 32349352, 2020). "After blocking the mevalonate pathway by statin and dipyridamole, HMGCS1 exerts nonmetabolic functions in enhancing gastric cancer progression." (PMID 32349352, 2020). "This study indicated that HMGCS1 had both metabolic and nonmetabolic functions in potentiating gastric cancer progression." (PMID 32349352, 2020). "According to stage classification, the mRNA expression of HMGCS1 was increased in stomach adenocarcinoma specimens from patients with advanced gastric cancer (stages I to III), compared with those of the adjacent nontumor tissues." (PMID 32349352, 2020). "The data showed that HMGCS1 could localize into nuclei, upregulate Oct4 and SOX-2 levels, and bind to Oct4 and SOX-2 promoters in gastric cancer cells." (PMID 32349352, 2020). "Our results reveal that HMGCS1 contributes to gastric cancer progression in both metabolic and nonmetabolic manners." (PMID 32349352, 2020). "HMGCS1 may activate the ISR pathway by associating with PERK, which, in turn, augments gastric cancer progression in a nonmetabolic manner." (PMID 32349352, 2020). "Next, we questioned whether HMGCS1 contributes to gastric cancer progression in a nonmetabolic manner besides the mevalonate pathway." (PMID 32349352, 2020). "Our study suggested that HMGCS1 could contribute to gastric cancer progression in a nonmetabolic manner." (PMID 32349352, 2020). "Therefore, under stress conditions, whether the translocation of cytosolic HMGCS1 into nuclei regulates gastric cancer progression through a nonmetabolic manner was analyzed." (PMID 32349352, 2020). "Using a similar mechanism, HMGCS1 could potentiate the ISR pathway and promote gastric cancer progression via a nonmetabolic pathway." (PMID 32349352, 2020).
hepatocellular carcinoma (5 papers, 2014 to 2025). A malignant tumor that arises from hepatocytes. "Mouse hepatoma cell lines 53.2b, 55.1c, 70.4, and Hepa1c1c7 were screened for their expression of Hmgcs1 and Hmgcr, encoding the first and rate-limiting steps in cholesterol biosynthesis." (PMID 25319454, 2014).
pancreatic cancer (5 papers, 2017 to 2025). "Additionally, the overexpression of GGPS1, FDPS, GART, and 3-hydroxy-3-methylglutaryl-CoA synthase 1 (HMGCS1) was also associated with a highly significant overall reduction in the survival duration of patients with esophageal and pancreatic cancers." (PMID 33670680, 2021). "In particular, we observed normalization of expression of KRAS, which is directly related to pancreatic cancer progression, and mevalonate pathway related genes (HMGCS1, MVD, MVK, and PDSS1)." (PMID 29262834, 2017). "Moreover, experiments by others demonstrated that hypoxia-induced upregulation of HMGCS1 can enhance lipid metabolism reprogramming to promote NE trans-differentiation in pancreatic cancer." (PMID 39014441, 2024).
acute myeloid leukemia (4 papers, 2022 to 2025). Acute myeloid leukemia (AML) is a group of neoplasms arising from precursor cells committed to the myeloid cell-line differentiation. "Hymeglusin (L-659,699) is the specific HMGCS1 inhibitor, and hymeglusin enhances the therapeutic efficacy of venetoclax in acute myeloid leukemia." (PMID 37958351, 2023). "HMGCS1 drives drug resistance and is suggested to serve as a target for the treatment of acute myeloid leukemia patients." (PMID 37958351, 2023).
diabetes (3 papers, 2017 to 2024). "Unanswered questions in the present study include the mechanism of PKCδ activation under diabetes, the sites of PKCδ phosphorylation, and the regulatory mechanism between PKCδ and HMGCS1/HMGCR, all of which require additional investigation." (PMID 38811564, 2024).
glioma (3 papers, 2017 to 2021). A benign or malignant brain and spinal cord tumor that arises from glial cells (astrocytes, oligodendrocytes, ependymal cells). "We found that circRNAs (hsa_circ_0072389, hsa_circ_0072386, hsa_circ_0008621, hsa_circ_0072387, and hsa_circ_007239) that bind to miR-338-5p in glioma were all transcribed from the same host gene HMGCS1." (PMID 34897031, 2021). "Through the GEPIA database, we found that the change in HMGCS1 mRNA expression in glioma was not statistically significant when compared with the control group." (PMID 34897031, 2021). "We also observed that the overexpression of HMGCS1, GGPS1, FDPS, and GART in breast, ovarian, endometrial, pancreatic, and CNS cancers correlated well with a reduction in the overall survival of patients when compared with that of patients without overexpression of these genes." (PMID 33670680, 2021). "Genes in the mevalonate pathway (ACAT2, HMGCS1, and HMGCR) and downstream in the cholesterol biosynthetic pathway (FDPS, FDFT1, and SQLE), were all downregulated in dense NHAs but not dense glioma TS lines." (PMID 28118603, 2017).
Hepatic steatosis (3 papers, 2008 to 2018). Steatosis is a term used to denote lipid accumulation within hepatocytes. "Whether HMGCS1 activation is specific to HCV core expression or is subsequent to hepatic steatosis demands further clarification." (PMID 18307821, 2008). "Our results demonstrate that aside from SREBPs themselves, HMGCS1, the crucial enzyme for the SREBP pathway, also plays some role in HCV core related hepatic steatosis." (PMID 18307821, 2008).
nasopharyngeal carcinoma (3 papers, 2024 to 2025). A carcinoma arising from the nasopharyngeal epithelium. "P4HA1 promotes nasopharyngeal carcinoma progression by activating HMGCS1, which inhibits erastin-induced ferroptosis and supports the proliferation and survival of both adherent and ECM-detached tumor cells." (PMID 40959429, 2025). "Moreover, P4HA1 can also activate HMGCS1 to promote nasopharyngeal carcinoma progression." (PMID 41469036, 2025).
Alzheimer disease (2 papers, 2018 to 2023). A progressive, neurodegenerative disease characterized by loss of function and death of nerve cells in several areas of the brain leading to loss of cognitive function such as memory and language. "In fact, as a regulator of cholesterol synthesis/metabolism, HMGCS1 shows reduced expression in Alzheimer’s disease." (PMID 38002279, 2023).
cervical squamous cell carcinoma (2 papers, 2020 to 2022). A squamous cell carcinoma arising from the cervical epithelium. "A study on cervical squamous cell carcinoma found that HMGCS1 were remarkably downregulated in tumor tissues compared with adjacent tissues, and knockdown of HMGCS1 supported anchorage-independent cancer cell growth." (PMID 35242038, 2022). "miR‐223 targeted the 3′‐UTRs of TGFBR3 and HMGCS1 and suppressed their expression, leading to increased anchorage‐independent growth and cervical squamous cell carcinoma (CSCC) tumor growth in vitro and in vivo." (PMID 32491253, 2020).
hyperlipidemia (2 papers, 2021 to 2024). "Compared with the NFD group, the PPARα protein and HMGCS1 protein of the hyperlipidemia rats induced by HFD decreased significantly, while the expression of the HMGCR protein increased significantly." (PMID 34681767, 2021). "Ursolic acid inhibits HMGCS1 activity, reducing cholesterol-related metabolite production and may explaining its therapeutic effects against hyperlipidemia and atherosclerosis and related disorders." (PMID 39359475, 2024).
leukemia (2 papers, 2022 to 2024). A malignant (clonal) hematologic disorder, involving hematopoietic stem cells and characterized by the presence of primitive or atypical myeloid or lymphoid cells in the bone marrow and the blood. "Collectively, the data presented here demonstrate that HMGCS1 promotes leukemia cell growth and drug resistance possibly through activation of the MAPK signaling cascade and elevation of the cholesterol level." (PMID 38994525, 2024). "Here, we demonstrate that HMGCS1 not only promotes leukemia cell proliferation but also impairs the efficacy of standard anti-leukemia regimens in AML." (PMID 38994525, 2024). "This discrepancy in sensitivity to hymeglusin may be attributed to the positive increase in the expression levels of HMGCS1 and multiple upregulated pro-leukemia genes in KG-1 cells." (PMID 35847946, 2022).
liver cancer (2 papers, 2024 to 2025). An epithelial or non-epithelial malignant neoplasm that arises from the liver. "Significantly, HMGCS1 KD improved tumor survival in this orthotopic liver cancer model under both CD and HFD conditions." (PMID 38308184, 2024). "Our animal cancer models have demonstrated promising effect in controlling HFD‐induced liver cancer growth by CSN6 deletion or knocking down HMGCS1." (PMID 38308184, 2024). "In orthotopic liver cancer models, targeting CSN6 and HMGCS1 hinders tumor growth in both normal and high fat diet." (PMID 38308184, 2024). "Moreover, in orthotopic liver cancer model established by injecting Huh7 cells infected with AAV‐shHMGCS1 into liver, HMGCS1 KD diminished liver tumor growth and proliferation under both CD and HFD conditions." (PMID 38308184, 2024).
multiple myeloma (2 papers, 2020 to 2024). "A statin-dependent upregulation of HMGCS1, together with other genes belonging to the mevalonate pathway, has also been described in multiple myeloma cells." (PMID 32692762, 2020).
ovarian carcinoma (2 papers, 2018 to 2021). A malignant neoplasm originating from the surface ovarian epithelium.
arteriosclerosis (1 paper, 2020). A vascular disorder characterized by thickening and hardening of the walls of the arteries. "Presence of arteriosclerosis associated significantly with expression of SQLE, FDPS, MVD, HMGCS1, HSD17B7 and HSF1 (all p≤0.05)." (PMID 32353828, 2020).
cataract (1 paper, 2022). Partial or complete opacity of the crystalline lens of one or both eyes that decreases visual acuity and eventually results in blindness. "SCR rats that are genetically predisposed to cataracts are reported to have mutations in Lss and Fdft1, which encode lanosterol synthase and farnesyl diphosphate farnesyltransferase, respectively, and which, like Hmgcs1 and Idi1, are involved in the cholesterol synthesis pathway." (PMID 36477544, 2022).